BRCA1 (BRCA1 DNA repair associated)
Diseases named in the same sentence as BRCA1 in open-access papers (continued):
Sharing a sentence is not in itself a finding about the gene and the disease.
tumor (continued). "By contrast, in the HRwt tumors, the stromal cell metaclusters had as many significant correlations with immune subtypes (n = 4) as with the tumor cell metaclusters (n = 4), suggesting distinct shaping of the immune microenvironment by the tumor cell subpopulations in the BRCA1/2mut tumors." (PMID 35149709, 2022). "BARD1, a known tumor suppressor, is an obligatory binding partner of BRCA1." (PMID 36187937, 2022). "“BRCAness” is used to describe cases in which homologous recombination repair (HRR) defects exist in a tumor in the absence of a germline BRCA1 or BRCA2 mutation." (PMID 35626055, 2022). "When comparing HRD-LOH scores between BRCA1 and BRCA2 mutated tumours in both breast and ovarian cohorts, an analysis not performed in the smaller TCGA dataset, the scores were slightly higher for BRCA1 compared with BRCA2 for both tumour types." (PMID 34979999, 2022). "Functionally, BARD1 protein acts as a tumor suppressor in BRCA1-dependent/independent pathways." (PMID 35650591, 2022). "To confirm these clonal observations, we also established single cell clonal expansions from the TM00099 PDX model, a TDP type 1 TNBC established from a post-treatment patient tumor and exhibiting partial methylation at the BRCA1 promoter when assessed in the bulk tumor." (PMID 35857626, 2022). "Besides ATR mutations, common mutated genes (BRCA1, EGFR, and ROS1) that characterize LUAD were also found in 5 tumor samples." (PMID 35712480, 2022). "Other immune evasion mechanisms included the upregulation of immune checkpoints such as programmed cell death-1 (PD-1) and the overexpression of vascular endothelial growth factor A (VEGF-A) an inducer of tumour angiogenesis, commonly seen in BRCA1/2-mutant HGSOC." (PMID 36159999, 2022). "Cells carrying the heterozygous BRCA1/2 mutation result in tumours that carry a DNA mismatch repair (MMR) deficiency unlike normal cells." (PMID 35805770, 2022). "This is because only proliferation, not the chance of tumor landing, is affected by the loss of BRCA1 function." (PMID 34996912, 2022). "However, it partially addresses the problem of BRCA1 displaying benign tumor characteristics in ultrasound." (PMID 35402620, 2022). "In the MINAS historical subgroup it was estimated that 14.6% of patients (13/89) had at least one tumour type that was not typical of the relevant CSGs (e.g. renal clear cell carcinoma in a patient with variants in both BRCA1 and MLH1)." (PMID 34983940, 2022). "Since reflex BRCA1/2 tumour genetic testing is typically arranged on a surgical specimen, this may be a function of decreased time from diagnosis to receipt of tumour genetic testing results." (PMID 35418215, 2022). "Although the proximity of Beclin1 to the BRCA1 tumor suppressor gene renders the interpretation difficult particularly in these tumor types, such a haplo‐insufficient tumor‐suppressive activity was also observed in the Atg5+/− mouse models for pancreatic cancer and AML." (PMID 35689420, 2022). "In addition, resistance to platinum doublets of chemotherapy was found to be greatly increased in patients with a KRAS mutation and low expression of the BRCA1 and TYMS genes in tumor tissue." (PMID 36294786, 2022).
tumor (continued). "We hypothesize that the isoform switch may represent a mechanism by which BRCA1 mutation-associated tumors can modulate BRCA2 transcript stability to retain HR function and enhance tumor survival." (PMID 36344544, 2022). "Third, as lymph node involvement has consequences for both treatment (regardless of tumor size), and prognosis in the general BC population, we evaluate the association between tumor size and lymph node status in BRCA1/2-associated BC patients." (PMID 35507134, 2022). "Upregulation of BRCA1 was related to tumor progression, platelet activation, and angiogenesis." (PMID 36118697, 2022). "Autoubiquitinated forms of BRCA1 act as tumor suppressors and inhibit their enzymatic function." (PMID 35874839, 2022). "Our results suggest that a greater ERCC1 expression in mt KRAS tumors might increase platinum resistance in this group of patients, whereas the greater expression of BRCA1 in wt KRAS tumor might be suggestive of the sensitivity of taxanes." (PMID 35877239, 2022). "Even if our study is limited to a little subset of PDAC and germline, analysis of variants identified on tumoral tissues was possible only in eight cases, it is noteworthy that NGS approach on tumor tissue let us to identify the exon 16 deletion of BRCA1 in the germline setting of a PDAC patient." (PMID 35625944, 2022). "To investigate this, here we analyze BRCA1 mutant mammary tissues and tumors derived from both BRCA1 mutant mouse models and human xenograft models to identify intrinsic determinants governing tumor progression and ICB responses." (PMID 35304461, 2022). "These loss-of-function RAD50 mutations could restrict MRE11-mediated degradation of nascent DNA at challenged replication forks in PARP-resistant, BRCA1/2-PALB2-mutated cells, and may help to explain tumor chemoresistance." (PMID 35501303, 2022). "In the second case, a germline BRCA1 frameshift mutation (c.1881_1884delCAGT p.(Ser628fs)) was not recognized by tumor sequencing because of poor coverage and sequence quality at the mutation site." (PMID 34202525, 2021). "Nine cases with germline variants in HR-related genes PALB2, BRCA1, RAD51C, FAN1 and CHEK2 also showed evidence of enrichment of the germline variant in the tumor, while the other 12 cases with HR-related gene variants (seven FAN1, three CHEK2, one BRIP1, one NBN) did not." (PMID 33917078, 2021). "Paired sample analyses for blood and tumor tissue were sequenced for BRCA genes (BRCA1 and 2)." (PMID 34152511, 2021). "The presence of a pathogenic BRCA1/2 or any HRR gene mutation in a tumor is not synonymous and interchangeable with HRD, and it does not necessarily signify a non-functional gene status." (PMID 34141624, 2021). "In this regard, although BRCA1 suppresses tumorigenesis, it may dichotomously promote tumor progression." (PMID 33888730, 2021). "In addition, Brca1 CpG promoter methylation was raised, and Brca1 and Erα mRNA expression were lowered in peritumoral and tumor mammary tissue compared to control rats." (PMID 34734210, 2021). "Interestingly, very weak Brca1 and Gata3 expression were observed in less than 10% of p18mt;Brca1+/- lung metastatic tumor cells, while Gata3 was barely detectable in p18mt;Brca1+/- lung metastasis." (PMID 34373738, 2021). "Although both somatic and gBRCA1/2 aberrations, resulting in high tumor TMB, have been approved by the FDA to function as a companion diagnostic tool for only BRCA1/2-mutated OCs, the antitumor activity of PARPi in BRCA wild-type tumors has been gaining attention, called “beyond BRCA” efficacy." (PMID 34930377, 2021).
tumor (continued). "Various tumor suppressor genes such as p16, MutL homolog 1 (MLH1), and breast cancer type 1 susceptibility protein (BRCA1) which are involved in DNA repair, cell cycle, cell adhesion, and apoptosis have been shown to undergo tumor-specific silencing by hyper methylation." (PMID 33883026, 2021). "Topical radiological or surgical ablation may be considered for the management of patients with oligometastatic disease, and the latter pattern of tumor appearance is characteristic for BRCA1/2-driven tumors exposed to platinum-based therapy." (PMID 34454564, 2021). "The objective of this review is to look at the role of BRCA1/2 mutations in the context of TME and plausible mechanisms by which the mutation-carrying TME might contribute to aggressive behavior of the tumor cells." (PMID 33540843, 2021). "This creates an excess in the amount of substrates for recombination repair, which in HR-deficient cancer cells, such as BRCA1 mutated tumours, is limited to repair by lower-fidelity NHEJ, leading to chromosomal aberration such as radial chromosomes and selective death of tumour cells." (PMID 34102225, 2021). "(Note, this gene pair would likely not have been detected with our method since it is based on induced essentiality: PARP mutations alone are not beneficial for the tumor and only become essential after mutation of BRCA1/2)." (PMID 34615983, 2021). "Tumours from women who tested BRCA PV negative in the high-risk cohort were more likely to be grade 1 than both BRCA1 (p < 0.001) and BRCA2 (p = 0.04) tumours." (PMID 34312777, 2021). "Despite being a multifunctional protein, the BRCA1 tumour suppressive function is mainly ensured by its ability to maintain genomic integrity through regulation of diverse cellular processes, including DDR, cell cycle checkpoint, apoptosis, chromosome instability, among others." (PMID 34298653, 2021). "Mutations in BRCA1 are known to confer defects in DNA repair and increase sensitivity to DNA damage, suggesting that a lower dose of irradiation might be needed to kill BRCA1 mutant tumor cells." (PMID 33767581, 2021). "As BRCA1 suppresses tumor growth, we hypothesized that full BRCA1 dosage might inhibit tumorigenesis, while BRCA1 suppression by FGFR2 signaling could weaken this inhibition." (PMID 34514747, 2021). "A few of the major tumor suppressors like BRCA1 and RB may impact or regulate BLM or could be a common target of tumor suppressors." (PMID 33777104, 2021). "Though pathogenic mutations in the RING domain are common, it is unclear whether the E3 ligase activity of BRCA1 is important for tumor suppression." (PMID 35008272, 2021). "Interestingly, BRCA1 also interacts with other transcription factors, drawing attention to this role of BRCA1 in its tumour suppression activity." (PMID 33755171, 2021). "After the exclusion of 522 BRCA1/2 carriers, stage (ORstage II vs stage I 1.33 [1.03 to 1.72]), tumor size (OR2–5cm vs ≤2cm 1.92 [1.33 to 2.77]), and subtype (ORluminal B [HER2-] vs luminal A 1.46 [1.04 to 2.05]) remained significantly associated with PTV34genes carriership." (PMID 34857041, 2021). "In this study, 10% (10/96) of BRCA1/2 PV identified in tumor samples were large CNVs." (PMID 33030818, 2021). "Interestingly, STING-activity is also upregulated in the setting of DDR deficiencies including BRCA1/2 and ATM mutant tumor cells." (PMID 34631532, 2021).
tumor (continued). "Furthermore, although AZD8835 and AZD5363 were efficient in reducing tumor progression, the use of AZD8835 further inhibited the activation of BRCA1/2 mRNA expression in KRAS-mutated cell lines." (PMID 34680390, 2021). "However, the tumor VAF of germline BRCA1/2 PV (n = 15) was all greater than 44% VAF (44–94%), versus the germline VUS (n = 17) which ranged from 5% to 90% VAF." (PMID 33030818, 2021). "A total of 232 tumour BRCA1/BRCA2 results were available at the time of analysis from NELCN cases." (PMID 34503154, 2021). "Moreover, the CHEK2 gene is HRR-related and was altered in one tumour (with a concomitant BRCA1 alteration)." (PMID 34680387, 2021). "BRCA1 (breast cancer 1, early onset) is a tumor-suppressor protein that plays a critical role in maintaining genomic integrity through regulation of important cellular processes, including genetic stability, DNA damage repair, centrosome duplication, apoptosis, and cell-cycle control 1-3." (PMID 33767581, 2021). "If the repair of DNA is inhibited, it will induce apoptosis to clear the cells that may be mutated; however, once BRCA1/BRCA2 is mutated, DNA repair cannot be completed, and the progression of tumor development is promoted." (PMID 34198652, 2021). "Mutually exclusive CTG expression with inactivating mutations in the major HR genes, BRCA1 and BRCA2, that drive tumor formation may indicate functional significance." (PMID 34481156, 2021). "Generally, it is the tumor suppressor gene and consists of two genes, i.e., BRCA1 and BRCA2; regarding its function, it has been reported that it has a role in DNA repairing mechanism, controlling the growth of the cell and blocking gene mutations, however, each with altered role on the targets." (PMID 34152511, 2021). "While there has not been as much evidence on differential methylation of DNA repair genes being involved in HGSOC chemoresistance, there has been one reported case of hypomethylation of BRCA1 in a relapsed HGSOC tumour sample in comparison to the patient’s primary tumour." (PMID 34885103, 2021). "A recent study reported that in patients with no germline pathogenic BRCA1/2 mutation, tumor tests were 100% concordant with no false positive results." (PMID 34073818, 2021). "Upon combined loss of BRCA1 and PALB2, massive apoptosis may occur due to excessively high ROS levels, despite further NFκB activation, leading to the loss of potential tumor-initiating cells and delayed tumor development." (PMID 33893322, 2021). "This signature has been related to deficient repair processes involving BRCA1 mutations but was not expected directly for a tumour arising from the variants in our candidate genes." (PMID 34045552, 2021). "BRCA1 R1443* PDX tumors at endpoint for vehicle showed diffuse H2AX staining across the entire tumor, whereas combination treated tumors showed intense H2AX foci and entire cells positive for H2AX, with significantly more intense staining in the combination treated tumors." (PMID 34465787, 2021). "Their results indicated that inflammasome activation in BRCA1 mutant tumor promoted tumor progression and that inhibition of inflammasomes could postpone tumor regression." (PMID 34452150, 2021). "Demographics and overall BRCA1/2 tumor results of study population." (PMID 33030818, 2021). "Similarly, in mouse models of BRCA1-deficient ovarian cancer, the cGAS-STING pathway was found to be critical for PARPi-dependent reduction of tumor size." (PMID 33978751, 2021). "One possible explanation is that low BRCA1 expression may be a marker of the methylator phenotype, in which areas of the genome, particularly surrounding tumor suppressors such as BRCA1, are silenced via methylation." (PMID 34611475, 2021).
tumor (continued). "Analyses of mouse mammary glands and cultured human cells showed that combined loss of BRCA1 and PALB2 led to high levels of reactive oxygen species (ROS) and increased apoptosis, implicating oxidative stress in the delayed tumor development in Brca1;Palb2 double CKO mice." (PMID 33893322, 2021). "Moreover, neutralizing CCL5 partly reversed PARPi-induced fibroblast activation and boosted the tumor inhibitory effect of PARPis in both BRCA1/2-mutant and BRCA1/2-wild type xenograft models." (PMID 34108603, 2021). "In our study, a significant association with grade was no longer seen after BRCA1/2 carrier exclusion, but other tumor characteristics common of fast-growing tumors, such as stage, tumor size, and luminal B [HER2−] subtype, remained significant." (PMID 34857041, 2021). "Nonetheless, the mutational profile of C. elegans brc-1 and brd-1 mutants is very similar to that found in BRCA1-deficient tumor cells, suggesting that TMEJ repair in the absence of BRCA1 contributes to carcinogenesis." (PMID 33996823, 2021). "Despite these advantages, challenges exist in BRCA1/2 tumor testing." (PMID 33030818, 2021). "The role of BRCA1/2 alteration in immunotherapy remains controversial across different tumor types." (PMID 33961040, 2021). "Furthermore, a previous study showed that LOH can confer a growth advantage in tumor cells, and the tumor suppressor genes BRCA1 and BRCA2 loci are frequently altered due to allelic imbalance during carcinogenesis in the breast." (PMID 35071399, 2021). "Two tumor suppressor genes, BRCA-1 and BRCA-2, play a role in DNA repair." (PMID 34660022, 2021). "As co-treatment with selinexor and olaparib exhibits anti-tumor activity regardless of BRCA1 mutation status, the clinical implications of the combination warrant further investigation." (PMID 34504648, 2021). "In our population, we found eight (5.7%) gBRCA1/2 VUS and six (4.3%) with tumor BRCA1/2 VUS." (PMID 34202525, 2021). "Olaparib is mainly effective in cells in which BRCA1/2 is not functional, such as tumor that have BRCA1/2 mutations." (PMID 33926008, 2021). "Last, we provide evidence that SP18–28 can be applied in BRCA1-deficient tumors and is not toxic to noncancerous cell lines, which would allow selective tumor killing." (PMID 33608267, 2021). "First, some important clinical and genomic data relating to T1bN0M0 TNBC, including Ki67, lymphovascular invasion, BRCA1/2 status, detailed lymph node status (isolated tumor cells or micrometastases), and TNBC molecular classification, are unavailable in the SEER database." (PMID 33391398, 2021). "We detected that p18−/−;Brca1MGKO tumor cells formed significantly more and larger spheres than p18−/− cells (data not shown) confirming the role of loss-of-function of Brca1 in stimulating TICs." (PMID 33478572, 2021). "BRIP1 acts as a tumor suppressor through its interaction with BRCA1." (PMID 35008774, 2021). "Implementation of our pathology-supported genetic testing (PSGT) strategy will enable BRCA1/2 screening in BC patients unselected by age or family history through integration of germline DNA testing with tumor gene profiling, as envisaged for future application of pharmacogenomics in Africa." (PMID 34660253, 2021). "However, both being tumor suppressors, BRCA1 and BRCA2 seem to be involved in different stages of DNA damage response and repair." (PMID 33525353, 2021).